WASF2 (WASP family member 2)
Description:
Downstream effector molecule involved in the transmission of signals from tyrosine kinase receptors and small GTPases to the actin cytoskeleton. Promotes formation of actin filaments. Part of the WAVE complex that regulates lamellipodia formation. The WAVE complex regulates actin filament reorganization via its interaction with the Arp2/3 complex.
Synonyms: WAVE2; SCAR2; IMD2; WASF4; dJ393P12.2
Tractability: Small molecule: a structure with a bound ligand is known. Antibody: UniProt places it where antibodies can reach, with high confidence; its Gene Ontology location is reachable by antibodies, with medium confidence; the Human Protein Atlas places it where antibodies can reach. PROTAC: ubiquitination databases record sites on it; its protein half-life has been measured.
Gene: Protein-coding gene on chromosome 1 (27,404,226 to 27,490,308, reverse strand). Ensembl gene ENSG00000158195.
Subcellular location: Cytoplasm, cytoskeleton; Cell projection, lamellipodium; Basolateral cell membrane
Subcellular location (Human Protein Atlas): Plasma membrane; Cytosol
Pathways (Reactome):
Signal Transduction: RAC1 GTPase cycle; RAC2 GTPase cycle; RAC3 GTPase cycle; RHO GTPases Activate WASPs and WAVEs; VEGFA-VEGFR2 Pathway
Disease: FCGR3A-mediated phagocytosis
Immune System: Regulation of actin dynamics for phagocytic cup formation
Gene Ontology:
Molecular function: cadherin binding; protein binding; protein kinase A binding; SH3 domain binding; actin binding; Arp2/3 complex binding; protein kinase A regulatory subunit binding
Biological process: negative regulation of stress fiber assembly; positive regulation of lamellipodium assembly; actin cytoskeleton organization; adenylate cyclase-modulating G protein-coupled receptor signaling pathway; positive regulation of Arp2/3 complex-mediated actin nucleation; postsynapse organization; postsynaptic actin cytoskeleton organization
Cellular component: basolateral plasma membrane; extracellular exosome; lamellipodium; protein-containing complex; SCAR complex; actin cytoskeleton; cytosol; cell-cell junction; cytoskeleton; early endosome; ruffle; synapse
Genetic constraint (gnomAD): Loss-of-function variants: 13 observed, 44.57 expected, observed/expected ratio (o/e) 0.29, 90% interval 0.19 to 0.46. The upper end of that interval is the gene's LOEUF score, 0.46, which puts it in group 2 of 6, group 1 being the genes least tolerant of losing a copy. Missense variants: 435 observed, 623.43 expected, observed/expected ratio (o/e) 0.7, 90% interval 0.64 to 0.75. Synonymous variants: 199 observed, 233.54 expected, observed/expected ratio (o/e) 0.85, 90% interval 0.76 to 0.96.
Homologues: Orthologues: chimpanzee WASF2 (100% identical), macaque WASF2 (99% identical), pig WASF2 (95% identical), rabbit WASF2 (94% identical), dog WASF2 (93% identical), guinea pig WASF2 (92% identical), mouse Wasf2 (92% identical), rat Wasf2 (91% identical), tropical clawed frog wasf2 (69% identical), zebrafish wasf2 (65% identical), Drosophila melanogaster SCAR (39% identical), Caenorhabditis elegans wve-1 (31% identical). Paralogues in human: WASF1 (51% identical), WASF3 (49% identical).
Diseases named in the same sentence as WASF2 in open-access papers:
WASF2 is named in the same sentence as 61 diseases in open-access papers, as found by Europe PMC text mining. Sharing a sentence is not in itself a finding about the gene and the disease. The quoted sentences say what the papers report.
breast carcinoma (22 papers, 2011 to 2025). "WASF2 is overexpressed in lung adenocarcinoma, breast carcinoma, pancreatic cancer, hepatocellular carcinoma, ovarian cancer, and its high expression is associated with poor prognosis, treatment resistance, and metastasis." (PMID 36902343, 2023). "In addition, WASF2 overexpression is clinically relevant in cancers such as melanoma, pancreatic cancer, and breast cancer as well as in liver metastasis in colorectal cancer." (PMID 35477411, 2022). "The Wasf2 complex regulates lamellipodia formation and is under regulation of PKD1-mediated pathways in the pancreas and breast cancer cells." (PMID 29258556, 2017). "Western blot data indicated that miR-1 overexpression significantly downregulated WASF2, TWF1, CNN3, TMSB4X and CORO1C, showing that miR-1 could inhibit breast cancer cell metastasis by targeting the WASF2, TWF1, CNN3, TMSB4X and CORO1C genes." (PMID 28159933, 2017).
melanoma (15 papers, 2017 to 2025). A malignant, usually aggressive tumor composed of atypical, neoplastic melanocytes. "WASF2 has been reported to be essential for the migration and invasion of mouse melanoma cells." (PMID 35849030, 2022). "It should be noted, however, that while WASF1 and WASF2 are not essential to invadopodium formation, WASF2, in particular, has attracted significant attention for its potential as a prognostic indicator and role in the invasion of cancers, like melanoma, breast, and pancreatic cancers." (PMID 33467681, 2021).
pancreatic cancer (12 papers, 2016 to 2025). "Out of their four-gene panel, they found that WASF2 had a greater connection with the risk of pancreatic cancer, even when compared to CA19-9." (PMID 40305328, 2025). "Monitoring serum levels of WASF2 mRNA may be particularly useful, as it was the most highly correlated with pancreatic cancer risk." (PMID 30358104, 2019). "Therefore, exosomal WASF2 might offer a new way to assess a patient’s risk of developing pancreatic cancer." (PMID 40305328, 2025). "In this research, we found that circular RNA hsa_circ_0000003(circ_WASF2) was upregulated in pancreatic cancer cells." (PMID 38704809, 2024). "Comparing serum levels of WASF2,ARF6,SNORA74A,SNORA25, and CA19‐9 revealed that levels of WASF2 were the most highly correlated with the risk of pancreatic cancer." (PMID 30358104, 2019). "We will investigate the upstream regulation of circ_WASF2 expression in pancreatic cancer." (PMID 38704809, 2024). "In future work, we will continue to investigate the function of circ_WASF2 in pancreatic cancer." (PMID 38704809, 2024). "The AUCs of WASF2,ARF6,SNORA74A, and SNORA25 in serum from patients in the early stages of pancreatic cancer (stages 0, I, and IIA) were > 0.9, compared with an AUC of 0.93 for the level of CA19‐9." (PMID 30358104, 2019). "The results of this study suggest that WASF2,ARF6,SNORA74A, and SNORA25 may be useful tools for the early detection of pancreatic cancer." (PMID 30358104, 2019).
glioma (6 papers, 2018 to 2024). A benign or malignant brain and spinal cord tumor that arises from glial cells (astrocytes, oligodendrocytes, ependymal cells). "Moreover, WASF2 has been associated with the viability and radioresistance of glioma cells via the WAVE2‐Arp2/3 axis." (PMID 35849030, 2022). "In addition, low expression of WASF2 in glioma was correlated with increased survival rate, whereas the ANKRD17 expression was suggested to have little effect on the survival rate of patients." (PMID 35849030, 2022). "The expression of ANKRD17 and WASF2 in glioma was predicted in the GEPIA system." (PMID 35849030, 2022). "WASF2 was suggested to be highly expressed in glioma, whereas the ANKRD17 expression was not significantly changed in glioma tissues compared to normal tissues." (PMID 35849030, 2022).
prostate carcinoma (6 papers, 2014 to 2023). A carcinoma that arises from epithelial cells of the prostate gland. "Among these 11 DGs, SLC7A11 can affect non-small cell lung cancer, renal cell carcinoma, prostate cancer progression through ferroptosis, and WASF2 is associated with poor ovarian cancer prognosis." (PMID 38035071, 2023). "SH3BP1 belongs to the Rho GTPase activating protein family and mediates cell motility 72, in a similar manner to that observed during EMT in prostate cancer, hepatocellular carcinoma (HCC) and cervical cancer via the Rac family small GTPase 1-WASP family member 2 pathway 73-75." (PMID 35982909, 2022).
hepatocellular carcinoma (5 papers, 2016 to 2025). A malignant tumor that arises from hepatocytes. "Epigenetic regulatory mechanism of WASF2 was assessed in the Cancer Genome Atlas liver hepatocellular carcinoma project (TCGA_LIHC) dataset and also validated in 38 paired HCC tissues." (PMID 35477411, 2022).
gastric cancer (4 papers, 2015 to 2017). A primary or metastatic malignant neoplasm involving the stomach. "In this context, the miR-1-mediated downregulation of the TMSB4X, CNN3, TWF1, CORO1C and WASF2 genes led to the inhibition of tumor cell metastasis of breast and gastric cancers." (PMID 28159933, 2017). "As previously reported, miR-146a suppressed the migration and invasion of gastric cancer cells by targeting WASF2." (PMID 28159933, 2017). "In the present investigation, miR-1 was shown to simultaneously inhibit tumor growth and metastasis of breast and gastric cancers by synchronously targeting CDK4 and TMSB4X, CNN3, TWF1, CORO1C and WASF2 genes." (PMID 28159933, 2017).
ovarian carcinoma (3 papers, 2022 to 2023). A malignant neoplasm originating from the surface ovarian epithelium. "A risk factor model was found to be predictive for OS in ovarian cancer based on the expression of WASF2." (PMID 35359421, 2022). "Our study demonstrated that WASF2 expression was associated with a poor prognosis and may be involved in the development of ovarian cancer, which might be explored as a potential prognostic marker and new targeted treatments." (PMID 35359421, 2022). "Finally, a risk factor model was found to be predictive for OS in ovarian cancer based on the expression of WASF2." (PMID 35359421, 2022). "Our studies revealed the possible roles of WASF2 across cancer, demonstrating that WASF2 would be a potential candidate for clinical biomarker, which could be used as a potential diagnostic and prognostic biomarker in many cancers, especially in ovarian cancer." (PMID 35359421, 2022). "The influence of silenced WASF2 on the proliferation of ovarian cancer cells was detected by the CCK8 assay, which showed that WASF2 knockdown significantly suppressed the proliferation of cells." (PMID 35359421, 2022). "Subsequent immunohistochemistry further confirmed WASF2 expression was significantly increased in ovarian cancer tissues." (PMID 35359421, 2022). "So, we further performed WGCNA analysis based on the expression profile data of ovarian cancer, and constructed the co-expression network related to WASF2 in ovarian cancer." (PMID 35359421, 2022). "At present, there is still no systematic molecular mechanism for the relationship between WASF2 and immune cells in ovarian cancer, which is innovative and worthy of further exploration." (PMID 35359421, 2022). "Meanwhile, it was further confirmed by immunohistochemistry that the higher expression of WASF2 in patients diagnosed with ovarian cancer." (PMID 35359421, 2022). "The results showed that the high expression of WASF2 mainly focused on mitotic spindle, UV response DN, Wnt/β-catenin signaling, heme metabolism, and G2/M checkpoint in ovarian cancer." (PMID 35359421, 2022). "Finally, we constructed a prediction model based on the expression of WASF2 and clinical symptoms to predict the prognosis of ovarian cancer and confirmed that the high expression of WASF2 in ovarian cancer." (PMID 35359421, 2022). "Accordingly, our functional studies demonstrated that downregulating WASF2 could suppress the proliferation, migration and invasion of ovarian cancer cells." (PMID 35359421, 2022). "Therefore, it is worthwhile to further study expression profile of WASF2 in human cancer, which provides new molecular clues about the pathogenesis of ovarian cancer." (PMID 35359421, 2022). "We found that the expression of WASF2 was significantly increased in ovarian cancer, suggesting that WASF2 might play an important role in the development of ovarian cancer, which would provide new insights for anti-tumor therapy." (PMID 35359421, 2022). "Based on the findings of the Cox regression analyses, we further constructed a nomogram integrating the age, grade, and the expression of WASF2, to provide a quantitative method for clinicians to predict the probability of 3‐ and 5‐year OS in ovarian cancer patients." (PMID 35359421, 2022). "Finally, the immunohistochemistry data confirmed that WASF2 were highly expressed in ovarian cancer." (PMID 35359421, 2022). "Functional bioinformatics analysis demonstrated that the WASF2 might be involved in several signaling pathways and biological processes of ovarian cancer." (PMID 35359421, 2022). "In addition, our analysis showed that WASF2 expression levels in ovarian cancer were correlated with four different types of immune-infiltrating cells (T cells gamma delta, Macrophages M2, Dendritic cells activated, Eosinophils)." (PMID 35359421, 2022). "Functional bioinformatics analysis demonstrated that the WASF2 may be involved in several signaling pathways and biological processes of ovarian cancer." (PMID 35359421, 2022).
ovarian carcinoma (continued). "Finally, our in vitro experiments demonstrated that silencing WASF2 inhibited the proliferation, migration, and invasiveness of ovarian cancer cells, and confirmed that WASF2 were highly expressed in ovarian cancer by immunohistochemistry." (PMID 35359421, 2022). "Moreover, in vitro experiments, it was demonstrated that the proliferative, migratory and invasive capacity of ovarian cancer cells was significantly inhibited due to WASF2 knockdown." (PMID 35359421, 2022). "In addition, we found that the silence of WASF2 could inhibit the proliferation, migration and invasion of ovarian cancer cells." (PMID 35359421, 2022). "Our enrichment analysis indicated that WASF2 could potentially impact etiology or pathogenesis of ovarian cancer by functioning in mitotic spindle, genes down-regulated in response to ultraviolet radiation, Wnt/β-catenin signaling, heme metabolism, and G2/M checkpoint." (PMID 35359421, 2022). "In addition, we constructed a nomogram that could be used for assessing the survival probability of patients with ovarian cancer based on age, stage and the expression of WASF2." (PMID 35359421, 2022). "We also compared WASF2 expression between epithelial ovarian cancer tissues and normal ovarian tissues by using immunohistochemical staining." (PMID 35359421, 2022).
colon cancer (2 papers, 2016 to 2023). "Expression of WASF2 was detected in colonic cancer cells, but not in normal colonic epithelial cells." (PMID 36902343, 2023).
aneurysm (1 paper, 2022). Bulging or ballooning in an area of an artery secondary to arterial wall weakening. "This MAPK node connected to LAMTOR3 and WASF2, two proteins identified in all three aneurysm groups." (PMID 35990960, 2022).
atherosclerosis (1 paper, 2020). A disease characterized by the build-up of fatty material and calcium deposition in the arterial wall resulting in partial or complete occlusion of the arterial lumen. "Modulation of WASF2 expression by miR-1253 in circulating PBMCs may contribute towards hypertension-related changes in membrane physiology and morphology and downstream complications, such as atherosclerosis." (PMID 32443852, 2020).
brucellosis (1 paper, 2024). Brucellosis is a bacterial infection that spreads from animals to people via unpasteurized dairy products or by exposure to contaminated animal products or infected animals. "In agreement with this, the expression levels of phagocytosis‐ and antigen‐presentation‐associated genes (e.g., CIITA, RFX5, HLA‐DPA1, WASF2) were reduced in brucellosis patients." (PMID 39135683, 2024).
colitis (1 paper, 2017). Inflammation of the colon. "Our results therefore revealed a key role of DICER/MiR-324-5p/HMGXB3/WASF-2 axis in maintaining the intestinal mucosal barrier, suggesting a new strategy for colitis and colitis associated CRC." (PMID 28915552, 2017). "Furthermore, in DSS induced colitis mouse model, AgomiR-324 by intraperitoneal injection significantly rescued the regulatory effects of Dicer on expressions of Hmgxb3 and Wasf-2 as evidenced by RT-PCR and immunohistochemistry staining." (PMID 28915552, 2017).
cyst (1 paper, 2017). A sac-like closed membranous structure that may be empty or contain fluid or amorphous material. "However, cyst-lining epithelial cells in Pkd1-deficient kidneys showed reduced and disorganized actin cytoskeletons with significantly decreased levels of marker genes such as Wasf2, Dock1, and Itga4." (PMID 29074972, 2017). "Inhibiting Wasf2 expression accelerated cyst growth, dysregulated actin structure, and decreased cell migration." (PMID 29074972, 2017). "In addition, knocking down Wasf2, Dock1, or Itga4 promoted cyst growth with actin cytoskeleton defects in 3D culture conditions." (PMID 29074972, 2017). "However, miR-182-5p inhibition could not slow cyst growth in Pkd2f/f:Aqp2-cre mice because Wasf2, Dock1, and Itga4 play significant roles in Pkd1 but not in Pkd2 conditional KO mice." (PMID 29074972, 2017).
Hypertension (1 paper, 2020). The presence of chronic increased pressure in the systemic arterial system. "Together, we have identified novel roles for miR-1253 and WASF2 in a hypertension-related disparities context." (PMID 32443852, 2020). "Our findings indicate that WASF2 may also be a player in immune cell cytoskeletal dynamics and future studies will help elucidate this contribution to any additional hypertension-related mechanisms." (PMID 32443852, 2020). "Our finding highlights the need to validate whether miR-1253 regulates WASF2 expression in primary endothelial or VSMCs, particularly in projects focused on examining mechanisms of hypertension-related disparity and in biospecimens from these populations." (PMID 32443852, 2020). "We identified differential expression of WASF2 between AA and white women with hypertension." (PMID 32443852, 2020). "However, our study is limited because it is not known whether differential expression of miR-1253 or WASF2 in AA women with hypertension is a contributing cause or a consequence of elevated high blood pressure." (PMID 32443852, 2020). "Here, we found that miR-1253, identified in our previous analysis but without a functionally validated role in hypertension, was predicted to target WASF2 in the actin cytoskeleton pathway." (PMID 32443852, 2020).
liver disease (1 paper, 2022). "WASF2 expression was increased in the HCC tissues from six public omics databases and increased significantly according to the progression of liver disease." (PMID 35477411, 2022).
ovarian serous cystadenocarcinoma (1 paper, 2014). A malignant serous cystic epithelial neoplasm arising from the ovary. "We found three WASF2–FGR fusions (in lung squamous carcinoma, ovarian serous cystadenocarcinoma and skin cutaneous melanoma), harbouring the exact same breakpoints in all cases." (PMID 25204415, 2014).
renal clear cell carcinoma (1 paper, 2022). "Furthermore, analysis of renal clear cell carcinoma showed that GNB1 was correlated with WASP family member 2 (WASF2), Neuropilin-1 (NRP1) and huntingtin interacting protein 1 (HIP1) of the vascular endothelial growth factor (VEGF) signaling pathway." (PMID 35193469, 2022).
systemic lupus erythematosus (1 paper, 2020). An autoimmune multi-organ disease typically associated with vasculopathy and autoantibody production. "In the third trimester, systemic lupus erythematosus and proteasome were enriched in the acute disease while Fc gamma R-mediated phagocytosis (VAV1, MARCKSL1, WASF2, DNM2, HCK, MAP2K1 genes) and adherens junction (ACTG1, WASF2, SMAD4, CSNK2B, EP300 genes) represented the subclinical category." (PMID 32012176, 2020).
triple-negative breast carcinoma (1 paper, 2016). An invasive breast carcinoma which is negative for expression of estrogen receptor (ER), progesterone receptor (PR), and human epidermal growth factor receptor 2 (HER2). "Especially, miR-146a or − 146b acts as a metastasis suppressor in gastric and triple negative breast cancer cells, which is related with crosstalk between tumor suppressor or oncogenic factor including breast cancer metastasis suppressor 1 and WASF2." (PMID 26418898, 2016).